OR4A15 (olfactory receptor family 4 subfamily A member 15)
Description:
Odorant receptor.
Synonyms: OR11-118
Gene: Protein-coding gene on chromosome 11 (55,367,974 to 55,368,918, forward strand). Ensembl gene ENSG00000181958.
Subcellular location: Cell membrane
Pathways (Reactome):
Sensory Perception: Expression and translocation of olfactory receptors
Genetic constraint (gnomAD): Missense variants: 655 observed, 384.66 expected, observed/expected ratio (o/e) 1.7, 90% interval 1.6 to 1.82. Synonymous variants: 237 observed, 138.39 expected, observed/expected ratio (o/e) 1.71, 90% interval 1.54 to 1.9.
Homologues: Orthologues: chimpanzee OR4A15 (97% identical), mouse Or4a15 (83% identical), rat Or4a15 (82% identical), rat Or4a15b (82% identical), guinea pig OR4A15 (78% identical). Paralogues in human: OR4A5 (63% identical), OR4A47 (61% identical), OR4A16 (60% identical), OR4A8 (60% identical), OR4C13 (60% identical), OR4C46 (60% identical), OR4C6 (59% identical), OR4C5 (59% identical), OR4C12 (58% identical), OR4C3 (58% identical), OR4C45 (57% identical), OR4C15 (56% identical), and 116 more.
Diseases named in the same sentence as OR4A15 in open-access papers:
OR4A15 is named in the same sentence as 1 disease in open-access papers, as found by Europe PMC text mining. Sharing a sentence is not in itself a finding about the gene and the disease. The quoted sentences say what the papers report.
cancer (1 paper, 2022). A tumor composed of atypical neoplastic, often pleomorphic cells that invade other tissues. "Of them, OR4A15 and OR6F1 belong to the olfactory receptor family, which can pair with the molecular secreted from neighboring neurons and is also highly expressed in different cancer tissues." (PMID 36000927, 2022).